FAP (fibroblast activation protein alpha)
Diseases named in the same sentence as FAP in open-access papers (continued):
Sharing a sentence is not in itself a finding about the gene and the disease.
pancreatic cancer (continued). "FAP-specific chimeric antigen receptor (CAR) T cells have also demonstrated effectiveness in eliminating FAP+ CAFs and curbing tumor growth in mouse models of lung, mesothelioma, and pancreatic cancers." (PMID 40173050, 2025). "Besides, the mRNA expression of FERMT2 positively correlated with ACTA2, COL1A1, FAP, and FSP based on TCGA pancreatic cancer data." (PMID 38910148, 2024). "PANC-1 cells are a type of epithelial tumor of human pancreatic cancer and our group previously verified the negative expression of FAP in this type of cell lines." (PMID 39281380, 2024). "For molecular imaging, tumor models with different levels of FAP expression were developed using the following cell lines: BxPC-3 (human pancreatic cancer), Panc-02 (murine pancreatic cancer), HT-1080 (human fibrosarcoma), and HT1080-FAP (HT1080 with stable overexpression of human FAP)." (PMID 38706713, 2023). "In COVID-19 infected patients, COL10A1/FAP/FN1 are also significantly upregulated, and FN1 may promote the progression of pancreatic cancer through the PI3K-AKT signaling pathway." (PMID 38063927, 2023). "Together, in this study, we identified the potent antitumor effects of FAP-targeted and CLDN18.2-targeted CAR-T cells sequential therapy in murine pancreatic cancer models at least partially through the improved accumulation of CAR-T cells and reduced recruitments of MDSCs to the tumor sites." (PMID 37046312, 2023). "Targeting CAF-derived cytokines and chemokines in combination with immunotherapies can improve anticancer efficiency such as when targeting the CXCL12-CXCR4 axis reverses FAP + CAF-mediated immunosuppression and synergizes with anti-PD-L1 immunotherapy in pancreatic cancer." (PMID 37480115, 2023). "Next, we analysed how FAP-expressing cells were related to previously identified CAF subtypes, including inflammatory and myofibroblast-like CAFs and three distinct stroma subtypes in pancreatic cancer." (PMID 35296803, 2022). "Gene expression analysis across multiple cancer types using The Cancer Genome Atlas dataset showed elevated FAP mRNA levels in different tumor types with the highest median observed in breast (1014 RNA-Seq by Expectation Maximization [RSEM], n = 1082) and pancreatic tumors (1213 RSEM, n = 177)." (PMID 35608703, 2022). "FAP was also found to be an independent predictor of both PFS and OS in pancreatic cancer patients." (PMID 34771664, 2021). "The finding of FAP as an independent prognostic factor for both PFS and OS in PDAC demonstrates the likely immunosuppressive effects the protein has in the pancreatic cancer tumor microenvironment as well as the potential for finding treatment strategies involving it." (PMID 34771664, 2021). "It has been shown that the majority of fibroblasts in human pancreatic tumors as well as in tumors from KPC mice express FAP and low levels of α-SMA, whereas a subpopulation of FAP-positive cells exhibit elevated α-SMA expression (named as myo-fibroblastic CAFs “myCAFs”)." (PMID 33333727, 2020). "Some of these stromal targets are being evaluated in pancreatic cancer, either by depleting CAFs using CAF-related cell-surface markers, such as α-SMA or FAP, reprogramming CAFs into quiescent fibroblasts, or targeting interactions between CAFs and their surrounding microenvironment." (PMID 33207686, 2020). "In addition, direct targeting of FAP+ CAFs, was shown to increase recruitment of CD8+ T-cells and subsequent tumor control in murine models of lung, colon and pancreatic cancer." (PMID 31731701, 2019). "Similar results were observed in murine models of pancreatic cancer, where FAP-CAR T cells significantly inhibited the growth of non-immunogenic tumor." (PMID 30987642, 2019).
pancreatic cancer (continued). "Although these studies support a functional role of FAP+ cells in immunosurveillance, the targeting of FAP+ CAFs, via adoptive transfer of FAP-targeted chimeric antigen receptor (CAR) T cells, can also suppress pancreatic cancer growth in mice by suppressing tumor angiogenesis." (PMID 29686035, 2018). "The significant correlation between stromal FAP expression and histological differentiation of PDAC prompted us to investigate whether stromal FAP expression affected the cell cycle of pancreatic cancer cells." (PMID 26330349, 2015). "FAP-dependent architectural/compositional alterations of the ECM promote tumor invasion along characteristic parallel fiber orientations, as demonstrated by enhanced directionality and velocity of pancreatic cancer cells on FAP+ matrices." (PMID 21668992, 2011). "Therefore, this study aimed to assess the ECM of pancreatic cancer using the fECV derived from enhanced CT images and integrating fECV with α‐SMA‐positive CAFs and FAP‐positive CAFs to investigate their relation to clinicopathological characteristics and prognosis in patients with PDAC." (PMID 41036616, 2025). "Another ongoing clinical trial (NCT03932565) evaluates intratumoral injection of Nectin4/FAP-targeted fourth-generation CAR-T cells (expressing IL-7 and CCL19, or IL12) for the treatment of Nectin4-positive advanced malignant solid tumors (NSCLC, breast, ovarian, bladder or pancreatic cancer)." (PMID 35211124, 2022). "Additionally, 18F-FDG PET/CT has low sensitivity and specificity in the diagnosis of pancreatic cancer, While FAPI PET/CT was found to show high tumor background contrast, and could visualize CAF density and crucial biological information on FAP expression." (PMID 35059319, 2021). "Therefore, FAP α is a link between the TME and pancreatic cancer cells, which indicates that blocking the activity of FAP α directly or depleting the FAP α-expressing cells may obtain the expected anti-tumor effects." (PMID 26985769, 2016). "The use of cells of different species (NIH-3 T3 cells generated from embryonic mouse fibroblasts and MiaPaCa-2 cells from human pancreatic cancer) may not be a confounding factor, because human FAP, not mouse FAP, was expressed in NIH-3 T3 cells." (PMID 26330349, 2015). "We investigated whether CAFs could be eliminated in tumor sites by FAP-targeted CAR-T cells and further improve the antitumor ability of CLDN18.2-targeted CAR-T cells by TME remodeling, aiming to develop an effective and safe pancreatic cancer treatment strategy." (PMID 37046312, 2023). "Although the potential utility of FAP immunohistochemistry and plasma FAP as a biomarker in renal tumors for the differential diagnosis at an early stage have previously been reported, there have to date been no comparable studies with respect to pancreatic cancer." (PMID 36263225, 2022). "Targeting specific stromal components, for example by inhibiting fibroblast activation protein (FAP), which was previously shown to reduce stromatogenesis in KRAS driven tumors of different tissues, may also reduce the stimulatory effect of the micro-environment on pancreatic tumors." (PMID 24213498, 2012). "Immunocytochemistry for FAP and α-SMA on primary isolated cells confirmed positive staining in fibroblasts from both CRE and KPC mice, whereas PANC-1 pancreatic cancer cells showed no staining." (PMID 39811640, 2025). "However, FAP-reactive CAR T cells have now also been employed without significant toxicity and with the ability to enhance anti-tumor immunity in murine models of lung, colon and pancreatic cancer." (PMID 31731701, 2019).
colorectal cancer (94 papers, 2005 to 2026). A primary or metastatic malignant neoplasm that affects the colon or rectum. "FAP is a significant marker of cancer-associated fibroblasts and is closely linked to colorectal cancer invasion and metastasis." (PMID 39170615, 2024). "Among them, FAP has been reported to be associated with expression and prognosis in EC, colorectal cancer, and pancreatic ductal adenocarcinoma and is a marker of tumor-promoting CAF." (PMID 36418422, 2022). "Colorectal cancers with high levels of stromal FAP are associated with aggressive disease progression and survival." (PMID 32733792, 2020). "Colorectal cancer development is associated with the reduction of OXTR signaling since OXT can suppress FAPα and CCL-2 expressions and their associated CAC migration via OXTR." (PMID 31920487, 2019). "For over three decades the role of aspirin in reducing colorectal cancer risk has been explored in a number of settings; in particular, for high-risk patients with FAP, HNPCC, patients already treated for colorectal adenomas, and for colorectal carcinomas." (PMID 28641310, 2017). "Two patterns of expression are most frequently found: 1) FAP expression by cancer associated fibroblasts (CAFs) of the tumor stroma only (e.g. breast or colorectal cancer) or 2) by both the tumor stroma and the tumor cells (e.g. sarcoma)." (PMID 23937772, 2013). "As such, various stroma-related factors, such as an abundance of αSMA+ fibroblasts and high expression of fibroblast activation protein (FAP), are associated with aggressive disease progression, recurrence, and therapy resistance in pancreatic and colorectal cancer." (PMID 36860656, 2023). "Similar trends have been observed in other cancers such as non‐small cell lung cancer (NSCLC) and colorectal cancer, further supporting the role of FAP as a marker of aggressive disease." (PMID 41410015, 2026). "Pancreatic and colorectal cancer: Elevated FAP expression correlates with shorter overall and disease-free survival, higher recurrence, and increased metastatic potential." (PMID 41441395, 2025). "Supporting our findings, FAP+ fibroblasts and macrophages were also upregulated and co-localized in colorectal cancer tissues, where a synergistic cell–cell interaction network between these cell populations was identified." (PMID 40029570, 2025). "In line with the TCGA results, recent scRNA-seq studies also suggested that FAP-expressing fibroblasts exhibited tumor-promoting roles in lung cancer, colorectal cancer, and PDAC47,58,59." (PMID 39870619, 2025). "FAP-4-1BBL was studied in preclinical rhesus monkey model with colorectal cancer and human patients with epithelial ovarian cancer or NSCLC." (PMID 41441395, 2025). "It is being tested for various cancers, including pancreatic, esophageal, colorectal cancer, melanoma, cholangiocarcinoma, and other solid tumors with FAP overexpression." (PMID 39765634, 2024). "More specifically, it has been shown that FAP-dependent activation pathways contribute to the blockage of immune checkpoints in colorectal cancer cells." (PMID 39765634, 2024). "Experimental evidence through immunohistochemistry techniques have shown the elevated expression of FAP in colorectal cancer." (PMID 39579201, 2024). "FAP IHC by cancer type performed in the tissue microarrays demonstrated strong FAP expression in 50–100% of colorectal cancer cases." (PMID 37608378, 2023). "In colorectal cancer, FAP+CAF secretes TGFβ, which activates the classical TGFβ signaling pathway and induces transcriptional regulation of Snail1 and Twist1 target genes, leading to EMT in cancer cells." (PMID 37277751, 2023). "Colorectal cancer has the biological characteristics of high expression of FAP, which provides the foundation for targeted FAP imaging." (PMID 36675506, 2023). "FAP promoted colorectal cancer angiogenesis by stimulating the ERK and AKT signal transduction pathways." (PMID 37752545, 2023).
colorectal cancer (continued). "In colorectal cancer, FAP is characterized by over-expression in tumor cells and tumor stroma, and its expression level is a sign of the early development of CRC." (PMID 36675506, 2023). "With regard to the carcinogenesis, it is noteworthy that the colorectal carcinoma of the index patient carried pathogenic APC and KRAS mutations as observed in conventional sporadic and FAP- and MAP-related colorectal carcinomas." (PMID 35675019, 2023). "The selective expression pattern of FAP allows imaging of colorectal carcinoma lesions as small as 1 cm in diameter on 131I-mAbF19 scans." (PMID 37316886, 2023). "Here, we identify the presence of diversified tumor microenvironment landscape in colorectal cancer, in which FAP+ fibroblasts and SPP1+ macrophages are enriched in the tumor tissue." (PMID 35365629, 2022). "Fibroblast activation protein α (FAP), a protein involved in tissue remodeling, can sustain invasion of the adjacent tissue in cancer, and was reported to be overexpressed in colorectal cancer being correlated with survival." (PMID 35328635, 2022). "PET/CT scans of 68Ga-FAP-2286 confirmed significant uptake in neoplastic lesions and low presence in normal tissues of patients with either pancreatic, breast, ovarian, or colorectal carcinomas." (PMID 35608703, 2022). "Colorectal cancer (CRC) is characterized by FAP overexpression within neoplastic cells and the tumor stroma and is a marker seen early in the development of CRC." (PMID 34638433, 2021). "Another colorectal cancer study confirmed that FAP+ CAFs produce CCL2 and exert similar effects on myeloid-derived suppressor cells." (PMID 34490078, 2021). "CAFs with high FAP expression recruit myeloid cells by upregulating CCL2 secretion to promote immunosuppression in the colorectal cancer tumor immune microenvironment." (PMID 34305902, 2021). "Fibroblasts expressing the marker fibroblast activation protein-alpha (FAP) induced resistance to PD-1 inhibitors in colorectal cancer murine models by promoting immunosuppression, recruiting myeloid cells and inhibiting T cell activity." (PMID 32457745, 2020). "We sought to investigate FAP as a prognostic molecular marker in colorectal cancer (CRC) using immunohistochemical and transcriptomic data." (PMID 32733792, 2020). "Colorectal cancers with high FAP expression display an inflamed phenotype enriched for macrophages and monocytes." (PMID 32733792, 2020). "In patients with non-small cell lung cancer and colorectal cancer, elevated FAP expression was reported to be related with tumor progression and poor survival." (PMID 31979338, 2020). "Early work on FAP α-targeting monoclonal antibodies investigated the toxicity, imaging, and bio-distribution of a 131-labeled monoclonal antibody (131I-mAbF19) against FAP α in patients with hepatic metastases from colorectal carcinoma." (PMID 26985769, 2016). "Altogether, FAP is expressed in about 90% of most common cancer types like breast, lung and colorectal cancer." (PMID 23937772, 2013). "Most of the common types of epithelial cancers, including over 90% of breast, lung and colorectal carcinomas, contain abundant FAPα expression." (PMID 16507127, 2006). "In total, deregulation of PSG9 mRNA was detected in 78% (14/18) of FAP adenomas and 75% (45/60) of sporadic colorectal cancer cases tested." (PMID 15982419, 2005). "In the HA-rich colorectal cancer model, the cancer-associated fibroblast (CAF)-directed AbEn, TAVO423 (FAP × LRRC15 × HYAL trispecific antibody) achieved greater intratumoral HA depletion resulting in superior tumor growth inhibition compared to untargeted HYAL." (PMID 41228205, 2025). "However, disappointing results were shown in the treatment of depleting FAP-positive cells in clinical trials of metastatic pancreatic and colorectal cancers." (PMID 38459511, 2024).
colorectal cancer (continued). "In colorectal cancer, the SPP1+ Mφ were positively correlated with the tumor-specific FAP+ fibroblasts, and the high infiltration of SPP1+ Mφ and FAP+ fibroblasts was associated with poor anti-PD-L1 therapeutic effects, highlighting the important role of SPP1 in cancer development." (PMID 39691723, 2024). "Notably, SPP1+ macrophages have been shown to interact with FAP+ fibroblasts in colorectal cancer and can stimulate the generation of desmoplastic structures limiting T-cell infiltration." (PMID 39400127, 2024). "Moreover, FAP also has prognostic significance in colorectal cancer, and further analysis showed that FAP in central tumors combined with tertiary lymphoid structures has more prognostic value in predicting recurrence after radical resection." (PMID 38063927, 2023). "For FAP, intratumoral or stromal expression correlated with poor prognosis in several cancer entities, such as ovarian cancer, non-small cell lung cancer, and colorectal carcinoma." (PMID 36672341, 2023). "The correlation between the HGF expression (hepatocyte growth factor) and FAP (fibroblast activation protein) with an increase in the number of blood vessels and metastasis in colorectal cancer (127 samples), colorectal polyps (51 cases), and unaltered tissues (28 cases) was studied." (PMID 35330327, 2022). "In addition, FAP is closely related to the prognosis of lung adenocarcinoma, ovarian cancer, and colorectal cancer." (PMID 36010886, 2022). "Additionally, the high expression of FAP in colorectal cancer is related to angiogenesis and immune regulation." (PMID 35004767, 2021). "Notably, PSG9 was expressed in the morphologically normal mucosa of FAP patients with APC germline mutations, while its expression was rarely detectable in normal mucosa of sporadic colorectal cancers using in situ hybridization." (PMID 15982419, 2005). "Similarly, spatial single-cell studies in colorectal cancer revealed that enrichment of FAP+ fibroblasts and SPP1+ macrophages correlate with reduced benefit from anti-PD-L1 therapy, underscoring the immunosuppressive crosstalk between stromal and myeloid compartments." (PMID 41441395, 2025). "This means that tumor mesenchymal cells with high expression of FAP exist in early liver metastases of colorectal cancer and can be detected by FAPI PET/CT, which may make up for the lack of obvious FDG uptake caused by the small number of tumor cells in early liver metastasis." (PMID 36675506, 2023). "Furthermore, FAP is a promising therapeutic target for colorectal cancer." (PMID 36675506, 2023). "However, the role of FAP in colorectal cancer (CRC) cells remains to be elucidated." (PMID 34035230, 2021). "In IPF, SPP1+ macrophages are highly expanded in fibrotic lesions and cross talk with myofibroblasts to drive fibrotic changes; in colorectal cancer, there are direct interactions between SPP1+ macrophages and FAP+ fibroblasts expressing high levels of MMP1/3." (PMID 41489684, 2026). "This review outlines a roadmap for precision medicine in colorectal cancer by leveraging the iCMS/IMF framework to integrate pathology and digital pathology, molecular diagnostics, and therapy mapping with FAP-targeted imaging and therapy." (PMID 41303568, 2025). "Recently, single cell spatial analysis revealed the intricate relationship between FAP+ fibroblasts and SPP1+ macrophages in colorectal cancer patients." (PMID 37035187, 2023). "This shows that both FAP+ fibroblasts and SPP1+ macrophages are largely responsible for orchestrating the TME and they should be considered as a potential target for colorectal cancer." (PMID 37035187, 2023). "For example, both early- and late-stage colorectal cancer cell-derived exosomes can activate quiescent normal fibroblasts (α-SMA( −), CAV( +), FAP( +), VIM( +)) into CAF-like fibroblasts (α-SMA( +), CAV( −), FAP( +))." (PMID 37723510, 2023).